Y_RNA (Y RNA )
Gene: Miscellaneous RNA gene on chromosome 11 (88,099,995 to 88,100,105, forward strand). Ensembl gene ENSG00000206690.
Homologues: Orthologues: chimpanzee Y_RNA (99% identical), macaque Y_RNA (97% identical). Paralogues in human: Y_RNA (84% identical), Y_RNA (83% identical), RNY1 (82% identical), Y_RNA (82% identical), RNY1P7 (81% identical), Y_RNA (81% identical), Y_RNA (80% identical), Y_RNA (79% identical), RNY1P16 (78% identical), RNY1P5 (78% identical), Y_RNA (78% identical), Y_RNA (77% identical), and 93 more.